EPHA2 (EPH receptor A2)
Diseases named in the same sentence as EPHA2 in open-access papers (continued):
Sharing a sentence is not in itself a finding about the gene and the disease.
cancer (379 papers, 2004 to 2026). A tumor composed of atypical neoplastic, often pleomorphic cells that invade other tissues. "The multivariate analysis revealed that high expression of Exo‐EphA2 in cancer was associated with a shorter OS and was a significant negative prognostic factor (HR = 1.04, 95% CI: 1.00–1.09, p < 0.001)." (PMID 39757782, 2025). "EphA2 overexpression, activation, and its association with poor patient survival outcomes have been frequently reported in a wide range of cancer types." (PMID 41130297, 2025). "Overexpression of USP5 and EphA2 has been linked to various cancers, and both the proteins have attracted considerable attention for the development of new anti-cancer drugs." (PMID 39897046, 2025). "PTEN loss also substantially elevates the activity of a variety of tyrosine kinases, including Src kinase and EphA2, a receptor tyrosine kinase implicated in cancer progression." (PMID 41130297, 2025). "We adopted and refined a protocol that has already been implemented in our laboratory to study cancer-related mutations in the context of the EphA2-Sam/Ship2-Sam complex." (PMID 39942820, 2025). "First of all, Ship2 is a negative modulator of receptor endocytosis and its association through Sam–Sam interaction with EphA2 is likely connected to pro-cancer effects in cancer cells, as it also favors EphA2 ligand-independent pro-migratory roles." (PMID 39942820, 2025). "Of course, experimental validation and in vitro assays in diverse cancer cell lines are needed to undoubtedly associate antioncogenic effects with the EphA2-Sam/SASH1-Sam1 complex." (PMID 39942820, 2025). "Previous studies have revealed that high EphA2 expression and signaling are frequently detected in many cancers and are associated with poor patient outcomes." (PMID 40615663, 2025). "Increasing evidence also suggests that upregulation of EphA2 is associated with drug resistance in many human cancer types." (PMID 39056783, 2024). "Ship2 works as a negative regulator of receptor endocytosis and consequent degradation, and anti-oncogenic effects in cancer cells should be induced by hindering its association with EphA2." (PMID 38474536, 2024). "Another level of complexity associated with EphA2 action in cancer is its ability to form ligand-independent homotypic head–tail (HT) interactions between the amino terminus and the membrane proximal domain of neighboring EphA2 receptors." (PMID 39596256, 2024). "EPHA2, a receptor tyrosine kinase, has been implicated in various human diseases such as cancer and inflammatory disorders." (PMID 39717596, 2024). "In this review, we summarize the main mechanisms underlying EphA2 dysregulation in cancer, highlighting its molecular complexity." (PMID 39596256, 2024). "A search was first conducted through the COSMIC (Catalogue of Somatic Mutations in Cancer) database to identify cancer-related missense mutations positioned inside or close to the EphA2-Sam and Ship2-Sam reciprocal binding interfaces." (PMID 38474536, 2024). "There is also a need for ongoing research into the mechanisms underlying the roles of IL-13Rα2 and EphA2 in cancer progression, the development of resistance, and the interplay with the TME." (PMID 38612592, 2024). "In line with our observations in OS, increased sensitivity of cancer cells to cisplatin associated with EphA2 inhibition was previously observed in human gastric, lung, and esophageal cancer models." (PMID 39056783, 2024). "For most cancers, the main mechanism underlying EphA2 activity relies on its ligand-independent signaling, the so-called noncanonical pathway." (PMID 39596256, 2024). "While previous research has implicated EPHA2 as a key player in diseases like cancer and irritable bowel disease, our study marks the first to underscore its significance in OA." (PMID 39717596, 2024).
cancer (continued). "It is known that miR-200c-induced radiosensitivity, as well as invasion, migration, and tube formation reduction, is associated with EphA2 downregulation in human cancer cells." (PMID 36090890, 2022). "Activated AKT mediates phosphorylation at the Ser897 site of EphA2, which has been shown to then be associated with cancer progression." (PMID 35668076, 2022). "EphA2 belongs to erythropoietin-producing hepatocytes family and is a transmembrane tyrosine kinase growth receptor associated with the of various malignant tumors and involved in mediating VM formation." (PMID 35595748, 2022). "The diametrically contradictory functions of EphA2 in cancer (i.e., pro- and anti-oncogenic roles) have been linked to diverse modulation of cell migration and invasion operated by either the canonical or non-canonical signaling." (PMID 36142306, 2022). "ErbB2 regulates cell proliferation in cancer (i.e., mammary adenocarcinoma) and its activity is further amplified by association in cis with EphA2." (PMID 35096972, 2021). "In summary, a new EphA2-associated super-enhancer was identified in ten cancer cell lines in this study." (PMID 33712565, 2021). "Aberrantly overexpressed EphA2 has been implicated in promoting EMT through Wnt/β-catenin signaling in cancer." (PMID 35096972, 2021). "Since EphA2 linker phosphorylation has been widely implicated in cancer malignancy, our findings can inform further mechanistic studies of EphA2 function and therapeutic strategies to target EphA2 signaling." (PMID 34857764, 2021). "While EphA2 is expressed at low levels in adult normal tissues, it is overexpressed in several cancers, and this aberrant expression is often associated with poor prognosis given that unbound EphA2 is pro-oncogenic and promotes cell migration and metastasis." (PMID 33023262, 2020). "EphA2 is overexpressed in a broad range of cancers, and its expression is in many cases associated with poor prognosis." (PMID 33092175, 2020). "Promoted EPHA2 expression in cancer cells is linked to a dismal prognosis because of recurrence as a consequence of enhanced metastasis." (PMID 33087088, 2020). "Aberrant EphA2 signalling is implicated in a number of pathologies, including cancer, and strategies to modulate EphA2 clustering are under active investigation." (PMID 31862615, 2020). "The present manuscript reviewed the clinical associations and biological and cellular consequences of EphA2 overexpression in cancer." (PMID 32811512, 2020). "Overexpression of EPHA2 was observed in cell lines derived from many aggressive human cancers and is frequently associated with enhanced angiogenesis and invasion." (PMID 31060342, 2019). "EphA2 and EphB4 are upregulated in many types of cancers and are associated with increases in cancer malignancy and poor prognosis." (PMID 31333644, 2019). "Previous studies concerning the linkage between EphA2 and malignant tumors indicated that an elevated EphA2 found in malignant tumors was a result of deficient phosphorylation of EphA2 itself, leading to the consequent blockage of EphA2 degradation." (PMID 30176889, 2018). "For example, EphA2 has been implicated in both decreased and increased cell migration, and has been shown to both inhibit and promote cancer cell malignancy." (PMID 30271902, 2018). "Extracellular vesicle‐associated EphA2 secreted from senescent cells stimulates mitogenic pathway in cancer cells." (PMID 29392820, 2018). "Once released, sEV-associated EphA2 promotes cancer cell proliferation by activating the Erk pathway through EphA2/ephrin-A1 reverse signalling." (PMID 28585531, 2017). "In turn, EphA2 overexpression in cancer cells is associated with decreased expression of E-cadherin which leads to loosening of the intercellular interaction." (PMID 27110571, 2016). "The overexpression of EphA2 has been discovered in many cancers and is associated with primary tumor initiation, progression, angiogenesis and metastasis." (PMID 26510908, 2015).
cancer (continued). "Ephrin type-A receptor 2 (EphA2) is a receptor tyrosine kinase that is associated with cancer cell metastasis." (PMID 25351620, 2015). "Increased expression of EphA2 is found in many types of cancer and is associated with aggressive features." (PMID 25344320, 2014). "In other solid tumors like vulvar, cervical, endometrial, gastric and head/neck carcinomas, higher EPHA2 protein levels were also associated with advanced disease stages and/or poor survival." (PMID 25025847, 2014). "In stage II and III cancer, EphA4 and EphA2 were both significantly associated with shorter survival (p = 0.007 and 0.019), but only EphA2 was an independent prognostic factor (HR, 2.6; 95% CI, 1.1-6.3; p = 0.039)." (PMID 23738943, 2013). "EphA2 overexpression is common in cancers, and is associated with oncogenic activity, cell invasiveness, metastatic potential and poor prognosis." (PMID 21408136, 2011). "Further studies with the Haddock refinement interface were next carried out to verify how a few selected cancer-related mutations could affect the binding of EphA2-Sam to SASH1-Sam1." (PMID 39942820, 2025). "Thus, herein, to investigate a possible correlation between the formation of the SASH1-Sam1/EphA2-Sam complex and EphA2 activity in cancer, cancer-linked mutations in SASH1-Sam1 were deeply analyzed." (PMID 39942820, 2025). "Next, through docking studies, with the support of Haddock and AF2 structure predictions, we investigate if/how cancer-linked mutations in SASH1-Sam1 could affect binding to EphA2-Sam." (PMID 39942820, 2025). "Studying the EphA2-Sam/SASH1-Sam1 complex in the context of SASH1-Sam1 cancer-related variants could provide important insights for applications in the anticancer drug discovery field." (PMID 39942820, 2025). "The most well-studied interaction is exosomal EphA2 derived from tumor serum that contributes to vesicular pathfinding, angiogenesis, and cell migration via Eph-ephrin forward signaling and is a potential diagnostic biomarker for several cancers." (PMID 39850798, 2024). "Whether intervention on EphA2 using natural active ingredients to normalize cancer associated blood vessels can further raise the benefits remains to be further discovered in this study." (PMID 39050762, 2024). "However, in a ligand-free state, EphA2 presents with asymmetric homotypic HT interactions, which cause ligand-independent phosphorylation of S897 and oncogenic signaling in cancer cells." (PMID 39596256, 2024). "In cancer, EphA2 undergoes an oncogenic switch and a loss of dependence on its ligand Ephrin A1." (PMID 38072918, 2023). "Although EphA2 has been implicated in cancer, there are also studies suggesting it may have antitumorigenic roles." (PMID 36830852, 2023). "EPHA2 is one of the most prominent EPH receptor family members in cancer, as its overexpression has been linked to treatment resistance, metastatic potential and disease progression in several cancer entities and has been shown to affect both cell proliferation and cell migration." (PMID 36401637, 2023). "EphA2 has also been implicated in many diseases, including cancer." (PMID 35970390, 2022). "The role of EphA2 in cancer is controversial as opposite outcomes, linked to malignant transformation and progression, are induced by the ligand-dependent signaling (i.e., canonical pathway) respect to the ligand-independent signaling (i.e., non-canonical pathway)." (PMID 36142306, 2022). "EphA2 has been implicated in many physiological and pathological processes, including epithelial homeostasis, immune system function, angiogenesis, inflammation, atherosclerosis, parasitic infections, and cancer malignancy." (PMID 34857764, 2021). "Thus, our clinical data showed that a high level of EphA2 in circulating exosomes was associated with cancer progression." (PMID 33879771, 2021).
cancer (continued). "Besides cancer and infectious diseases, EPHA2 has been repeatedly linked with clouding of the eye lens or cataract(s)—a leading cause of visual impairment worldwide." (PMID 34685586, 2021). "These facts suggest the contribution of EV‐associated EphA2 to cancer development." (PMID 29392820, 2018). "Existing evidence has demonstrated that EphA2 expression is associated with cancer cell metastasis." (PMID 25351620, 2015). "Moreover, we describe Ad vectors entry-targeted to the highly relevant pan-cancer surface marker EphA2 by genomic insertion of the gene encoding the chimeric fiber or a CAR binding-ablated HAdV-5 fiber with YSA peptide ligand." (PMID 24760010, 2014). "The high level of EphA2 expression was identified to be associated with cancer outcome." (PMID 25013485, 2014). "Another group of differentially expressed proteins are associated with increased cancer cell motility and invasiveness, which include EphA2, BCAS1, S100 protein family members, Rho family members, Ral-A, Rab family members, Cdc42, MARCKS, Ezrin, Galectins 1 and 3 among others." (PMID 22417809, 2012). "EphA2 expression is frequently elevated in cancers and is associated with poor prognosis." (PMID 21264258, 2011). "In fact, SASH1 is a known tumor suppressor protein, whereas EphA2, although exhibiting often controversial functions, is associated with several pro-cancer activities; thus, this Sam–Sam interaction could be important to modulate the EphA2 cancer-related signaling pathway." (PMID 39942820, 2025). "Notably, the EphA2 is rarely mutated or amplified in cancer tissues." (PMID 33572284, 2021). "Activation of EpHA2 might cause invasiveness and migration of cancer cells." (PMID 33466719, 2021). "Thus, it is tempting to speculate that senescence-associated secretion of sEV-associated EphA2 may contribute to the age-related increase in cancer incidence." (PMID 28585531, 2017). "Both PRMT5 and EphA2 proteins are overexpressed and play a crucial role in multiple cancers, and have been used as targets to develop new anticancer drugs." (PMID 41930341, 2026). "Although preclinical and clinical studies targeting EphA2 have been conducted as cancer therapeutics, its role in the DNA damage response remains elusive." (PMID 41655696, 2026). "These interactions suggest the complex interplay between virulence factors of Candida species and host cell receptors in cancer, with EGFR, HER2, and EphA2 being receptor tyrosine kinases implicated in cancer progression." (PMID 40284554, 2025). "CAR-Ms showed significantly higher killing efficiency, confirming their specificity for CD19+ and EphA2+ cancer cells." (PMID 40595560, 2025). "When compared to the control group, the cancer group had a significantly higher serum level of Exo‐EphA2." (PMID 39757782, 2025). "Antibodies (Abs) that agonize and trigger internalization of EphA2 can be conjugated to cytotoxic drugs, and these ADCs have been used to deliver the drugs to cancer cells overexpressing EphA2." (PMID 40411427, 2025). "The proteomic results also indicated that the ephrin type-A receptor 2 (EphA2) expression was significantly increased in PAK4KO cancer cells." (PMID 41294859, 2025). "Suppression of EphA2 expression has been shown to harden spheroids and significantly reduce the cancer area, underscoring its role in metastasis." (PMID 40181964, 2025). "Recently, certain laboratories have attempted to utilize EphA2, a protein that is expressed on the surface of many cancer cells." (PMID 40109582, 2025). "Remarkably, EphA2 expression levels were consistently upregulated across all three cancer cell lines following PTEN knockdown." (PMID 41130297, 2025). "EphA2 overall effect in cancer cells derives from a fine balance between the mainly antioncogenic, ephrin ligand-dependent canonical pathway and the uncanonical pathway that does not rely on ephrin ligand binding and is mostly considered pro-oncogenic." (PMID 39942820, 2025).
cancer (continued). "This provides novel insight into EphA2’s impact on the immune landscape of NSCLC and the additional potential benefits of targeting EphA2 in cancer." (PMID 40867322, 2025). "Particularly, ephrinA2 receptor (EphA2) is the most frequently affected Eph receptor in the human cancers." (PMID 39897046, 2025). "Regarding antibody drugs, the Phase I trial of DS-8895a, a humanized anti-EphA2 defucosylated mAb, has been performed against advanced EphA2-expressing cancer." (PMID 40065768, 2025). "Gene pathway analysis yielded two significantly upregulated pathways in the EphA2-overexpressing tumors, cancer progression and macrophage functions, consistent with our prior observations." (PMID 40867322, 2025). "To target the EphA2-positive cancer cells by Ea2Mab-7 (mouse IgG1), we should generate a class-switched mouse IgG2a mAb from mouse IgG1." (PMID 40236294, 2025). "Specifically, EphA2 protein, which is sorted into sEVs secreted by senescent cells, can bind to ephrin-A1, a ligand highly expressed in various cancer cells, thereby promoting cancer cell proliferation through EphA2/ephrin-A1 reverse signaling." (PMID 40046513, 2025). "To validate the cell line data and characterize EphA2 expression in human cancers, we analyzed genomic data from The Cancer Genome Atlas (TCGA)." (PMID 40225586, 2025). "Using different cancer cell lines and genetic manipulation methods, we confirmed that PTEN loss leads to the EphA2 upregulation across different cancer types." (PMID 41130297, 2025). "Ephrin receptor A2 (EphA2), in particular, is overexpressed in a variety of cancers and is a proven target for anti-cancer drugs." (PMID 39695021, 2025). "To elucidate the roles of EPHA2 in cancer cell death, we conducted RNA sequencing (RNA-seq) on cells obtained from both the shControl and shEPHA2–1 groups." (PMID 40919148, 2025). "The proteomics study confirmed the enrichment of molecules in fibronectin and the VEGF pathway in PAK4KO cancer cells, along with the upregulation of EphA2, RhoA, ROCK1, ROCK2, and components of the EPH-ephrin signalling pathway, linking to enhanced VM." (PMID 41294859, 2025). "The high expression of EphA2 is observed in various cancers, which promotes cancer malignancy, whereas its levels are relatively low in most normal adult tissues." (PMID 40236294, 2025). "These pH-sensitive LYTACs (pH_LYTACs) induced more potent degradation of EphA2 in two different cancer cell lines, HCT116 and MDA-MB-231, as assessed by cell-surface staining and western blot, with dose-dependent degradation." (PMID 41256377, 2025). "In co-culture assays including CAFs and cancer cells, tyrosine phosphorylation of EphA2 on CAFs was increased, which led to enhanced invasiveness of cancer cells." (PMID 39780187, 2025). "Current research suggests the crucial involvement of RUNX1 and EPHA2 in angiogenesis and the invasion of cancer cells." (PMID 39797421, 2025). "Collectively, these data support a dual role of EphA2 in cancer as EphA2 action can be either pro- or antioncogenic." (PMID 39596256, 2024). "EA1.2, EA2, or B233 were among the first generated anti-EphA2 mAbs and showed efficacy in preclinical studies by inhibiting cancer cell growth both in vitro and in vivo." (PMID 39596256, 2024). "Inhibition of ligand-independent activation of EphA2 represents a potential target for cancer therapeutics." (PMID 38915729, 2024). "Several compounds targeting EphA2 were evaluated and tested in clinical studies of cancers in which the oncogenic function of EphA2 is well established." (PMID 38279277, 2024). "The use of physical barriers to interfere with EphA2 receptor-ephrinA1 ligand binding, clustering and subsequent lateral transport results in changes to the cellular response of EphA2 to ephrinA1 in cancer cells." (PMID 38534339, 2024).